IL6 (interleukin 6)
Diseases named in the same sentence as IL6 in open-access papers (continued):
Sharing a sentence is not in itself a finding about the gene and the disease.
asthma (continued). "Elderly people with asthma also exhibit greater sputum cytokines levels, including IL-6 and IL-1β, which were both associated with increased likelihood of hospitalization due to asthma." (PMID 37047327, 2023). "Knock-down of lncRNA CRNDE reduced the lung injury caused by the asthma induction, increased the IL-10 content, and decreased the contents of IL-17A and IL-6 considerably while reducing the number of Th17 cells in the spleen." (PMID 36743692, 2023). "The link of the asthma susceptibility SNP in IL6R to sIL-6Rα levels prompted us to further investigate IL-6 trans-signaling." (PMID 38062491, 2023). "The improper regulation of IL-6 triggers a cytokine storm associated with various autoimmune disorders, such as AD and asthma." (PMID 37175425, 2023). "One of the genes regulated by CRE, encoding IL-6, plays a crucial role in several inflammatory and airway diseases, such as asthma and COPD." (PMID 37569749, 2023). "Previous genome-wide association studies along with clinical studies have shown an association between IL-6 signaling and asthma." (PMID 38062491, 2023). "An IL-6 + sIL-6Rα gene signature score was associated with lower levels of sputum eosinophils in asthma." (PMID 38062491, 2023). "Sputum neutrophilia in asthma is strongly associated with increased production of several cytokines including IL-1β, IL-6, CXCL8, IL-12, IL-17A and TNF, and this correlates with bacterial burden, in particular Gamma-proteobacteria." (PMID 37180449, 2023). "IL‐6 has also been linked to a severe asthma phenotype with worse lung function and more frequent exacerbations, independently of BMI." (PMID 36973952, 2023). "Peripheral blood IL-6 has recently been identified as a potential biomarker for adult asthma, and IL-33 is a susceptibility gene for childhood asthma, while TSLP is associated with initiation and persistence of inflammatory pathways in asthma." (PMID 38106417, 2023). "Ultimately these studies show that, T-cell-lung fibroblast interactions cause release of cytokines such as IL-6, IL-8, and IL-23 which work to attract leukocytes to aid chronic inflammatory processes in asthma." (PMID 36911735, 2023). "Blood IL‐6 levels has previously been shown to be elevated in a severe asthma cohort and associated with increased exacerbations." (PMID 37114915, 2023). "In summary, although limited studies have reported serum IL-6 level in asthma, our findings associate higher levels of IL-6 in patients with asthma, especially in children with asthma." (PMID 37173781, 2023). "The genetic polymorphism in the IL-4Rα, which is associated with asthma exacerbation, potentiates the Th17 immune response in an IL-6-independent manner." (PMID 36032162, 2022). "TNF and IL-6 are the two cytokines with a broad spectrum of immunodulatory effects, yet in the context of asthma they both can be defined as pathogenic." (PMID 35408882, 2022). "In adults with asthma, an elevated level of serum IL-6 was associated with increased body weight, lower lung function and greater exacerbation risk." (PMID 35055456, 2022). "Previously, two meta-analyses examined the association between IL-6 rs1800795 polymorphism and asthma risk." (PMID 35368692, 2022). "IL-6 rs1800795 polymorphism was a protective factor against asthma, while it was associated with increased susceptibility to allergic rhinitis." (PMID 35368692, 2022). "As such, studies have shown that immune response phenotypes characterized by deficient IFN-γ and IL-6 are associated with worse clinical outcomes and higher risk of asthma exacerbations." (PMID 36366542, 2022). "The results revealed that there was a statistically significant association between IL-6 rs1800795 polymorphism and the risk of asthma and allergic rhinitis in the general population." (PMID 35368692, 2022). "Elevated IL6 levels were associated with reduced lung function and heightened asthma exacerbation risk." (PMID 36140412, 2022).
asthma (continued). "In the MR analysis, we identified putative causal associations of BMI on IL-6 levels and IL-6 on asthma risk in children after multiple testing, whereas the association of IL-6 with adult onset asthma was nominally significant." (PMID 36253437, 2022). "We also replicated the association of IL-6 with asthma and wheezing in the Boston Birth Cohort (BBC)." (PMID 36253437, 2022). "When we studied the association between IL-6 gene polymorphisms and each allergic disease separately, we found that the rs1800795 polymorphism was associated with a lower risk of asthma but was associated with increased susceptibility to allergic rhinitis." (PMID 35368692, 2022). "IL6 levels are associated with systemic inflammation, metabolic dysfunction, and greater asthma severity among lean and obese adults." (PMID 36140412, 2022). "Epidemiologic studies have found associations of an increased IL-6 level in the serum, sputum, and bronchoalveolar lavage fluid with asthma prevalence and its severity." (PMID 33912579, 2021). "IL-6 was reported to produce a pathogenic effect in an asthma model, the inactivation of which reduced eosinophilia in the lungs." (PMID 34608825, 2021). "The major allele C of rs4792901, a risk factor for the development of adult asthma, was associated with increased levels of serum IL6." (PMID 34552174, 2021). "IL-6 is elevated in asthmatic patients and it is suggested that IL-6 has a causative role in determining an increase in airway resistance in asthma and chronic obstructive pulmonary disease." (PMID 34725715, 2021). "Taken together, IL-6 is implicated in progression, severity and duration of asthma and should be considered as a target for anti-cytokine asthma therapy." (PMID 34084159, 2021). "The spike in neutrophils was accompanied by an increase in IL-6, which has been shown to be associated with asthma in humans." (PMID 33446928, 2021). "The presentation of IL-6 increase in asthma patients represented its vital pathogenic role in asthma." (PMID 34608825, 2021). "In patients with adult-onset asthma, elevated IL-6 was associated with high-dose inhaled corticosteroid use, systemic inflammation, and was linked to poor asthma control." (PMID 33925531, 2021). "A significant association was observed between baseline IL-6 level and the probability of experiencing an asthma attack treated with systemic corticosteroids during the 1-year study." (PMID 33925009, 2021). "High IL-6R mRNA and IL-6 protein sputum levels have been found associated with higher sputum neutrophils in patients with severe asthma." (PMID 33418879, 2021). "In the obese subjects with asthma, concentrations of the pro-inflammatory cytokines IL-6 and IL-8 decreased with weight loss." (PMID 33418879, 2021). "In asthma mice, macrophages and dendritic cells were found to be the key sources of pathogenic IL-6." (PMID 34608825, 2021). "Recently it was shown that IL-6/sIL6R induced loss of epithelial barrier integrity, which was related to a specific non Type 2 asthma phenotype." (PMID 33374733, 2020). "IL-6 plays a key role in acute phase response and is associated with a variety of clinical and biological parameters in asthma, COPD as well as ACO." (PMID 32448302, 2020). "IL-6 is an important regulator of pathogenesis in asthma and has also been implicated in subepithelial fibrosis and airway remodeling in asthma." (PMID 32670268, 2020). "Increased IL-6 response has been associated with onset of the viral upper respiratory tract infection in healthy individuals or virus-induced asthma exacerbations." (PMID 32811568, 2020). "As expected, in asthma concentration of IL-6 in BAL was associated with BAL and blood neutrophilia (β = 0.51 [95% CI 0.41–0.6] and β = 0.41 [95% CI 0.31–0.51], respectively)." (PMID 32685129, 2020). "In asthma, the IL-4R variant directs the reprogramming of inducible Tregs (iTregs) to Th17-like cells in an IL-6-dependent manner." (PMID 32871353, 2020).
asthma (continued). "This response, including secretion of IL-6, also triggers the proliferation of smooth muscle cells in the airways that causes pulmonary obstruction in asthma." (PMID 32641036, 2020). "In asthma, it has been reported that IL-6 is linked with mixed eosinophilic–neutrophilic bronchitis during exacerbations of the disease and worse pulmonary function in humans." (PMID 33066442, 2020). "First, inflammatory cytokines, including TNF-α and IL-6, are associated with an increased risk of asthma." (PMID 32999682, 2020). "The absence, or reduced concentration of IL-10, associated with asthma enables the continued secretion of pro-inflammatory cytokines that contribute to lower airway inflammation, including IL-6, IL-5, IL-4, TNF-α, and IL-1." (PMID 31694631, 2019). "IL-6 (-174-G/C) polymorphic study analysis depicted C allele as a risk of developing allergic conditions under study; asthma, rhinitis, conjunctivitis and food allergy except the dermatitis group which showed that G allele is risk allele for it." (PMID 31251775, 2019). "In the present study, we used conditional gene targeting to demonstrate that macrophages and dendritic cells are the critical sources of pathogenic IL-6 in acute HDM-induced asthma in mice." (PMID 30534125, 2018). "Taken together, our results demonstrate the pathogenic role of IL-6 in clinically relevant low-dose acute HDM-induced asthma model and reveal the distinct roles of IL-6 produced by macrophages and dendritic cells in acute allergic airway inflammation." (PMID 30534125, 2018). "Taken together, our results indicate that IL-6 plays a pathogenic role in the HDM-induced asthma model and that lung macrophages and dendritic cells are the predominant sources of pathogenic IL-6 but contribute differently to the disease." (PMID 30534125, 2018). "Using data from ALSPAC we assessed associations between serum CRP and IL-6, aged 9 years, atopic conditions (asthma and eczema) before age 10 years, and lifetime experience of hypomanic symptoms assessed at 22 years." (PMID 27476619, 2017). "The present study is the first to show that a hypercoagulable state in asthma, characterized by enhanced plasma thrombin formation, is associated with increased blood levels of inflammatory cytokines, IL-6 and TNFα." (PMID 28429138, 2017). "In men, improved lung function was associated with increased levels of IL-6, increased asthma-related quality of life and improved self-rated health." (PMID 28915273, 2017). "The mid-range cytokine levels of IL-6 were associated with better self-rated health and asthma-related quality of life in men." (PMID 28915273, 2017). "Increased FEV1 in men was associated with an increase in IL-6 (Rho = 0.24, p<0.05) as well as improved self-rated health (Rho = -0.21, p<0.05) and asthma-related quality of life (Rho = 0.29, p<0.01) over the year." (PMID 28915273, 2017). "Regarding the JPSS, the score was positively associated with IL-8 expression among subjects with asthma and/or allergic rhinitis and there was marginally significant association with IL-6." (PMID 26819847, 2016). "To mimic the inflammatory milieu in asthma we now examined the impact of OA (for 45 min) on IL-6 and IL-8 expression stimulated by TNFα – a pro-inflammatory cytokine implicated in asthma." (PMID 25985190, 2015). "The enhanced propensity of individuals with the P22L mutation to develop asthma is in line with the observed decreased capacity of IRAK-M with mutations in this region (P22A-A23S mutant) to down-regulate IL-6 expression in macrophages upon TLR2/4 stimulation." (PMID 25481771, 2014). "We aimed to evaluate the association between indoor radon exposure and plasma IL-6 levels in children with asthma and whether this relationship differs by allergic sensitization status." (PMID 42188340, 2026). "Systemic IL-6 inflammation has been further linked to metabolic dysfunction and asthma severity." (PMID 40599681, 2025).
asthma (continued). "On the other hand, IL-6 has been associated with a decrease in lung function in severe asthma and may induce mucus hypersecretion." (PMID 40599681, 2025). "Also, IL-6-targeted therapies have emerged as potential candidates, particularly for patients with metabolic dysfunction or obesity-associated asthma." (PMID 40806756, 2025). "Further, asthma is associated with increased production of IL-6." (PMID 40122610, 2025). "Moreover, the polymorphism pattern of IL-6 -174G/C gene subgroup analysis showed that the risk of mild asthma increased fourfold with the GG genotype pattern compared to healthy control, OR = 4.4, p < 0.001." (PMID 38388670, 2024). "Additionally, the study found that predictors of severe asthma, besides the dominant variation of IL-6 gene (-174G/C) polymorphism, were being older with childhood-onset disease." (PMID 38388670, 2024). "Moreover, a subgroup analysis by ethnicity and age revealed that among Caucasians, the IL-6 gene (− 174G/C) polymorphism decreased asthma risk in both the recessive and homozygote comparisons." (PMID 38388670, 2024). "The mRNA expression of the two evaluated pro-inflammatory cytokines associated with asthma development, namely IL-6 and IL-1β were significantly elevated in the lungs of HDM-challenged mice previously sensitized with HDM and CFA (p < 0.01), when compared to the normal-control animals." (PMID 39129025, 2024). "Animal studies revealed that the reduced levels of asthma-associated inflammatory factors IL-6 and IL-12 mRNA in DC cells knocked down for METTL3 may have been related to a defective TLR4/NF-κB signaling pathway caused by the deletion of METTL3." (PMID 39108751, 2024). "IL-6 represents another pro-inflammatory cytokine with an important role in respiratory diseases associated with inflammation but also in the pathogenesis of asthma and potentially COPD." (PMID 39239645, 2024). "This cytokine change may be the cause of these people’s heightened vulnerability to asthma since IL-6 plays a role in non-TH2-mediated asthma processes." (PMID 38892971, 2024). "IL-6 (produced in high amounts by M1 macrophages in adipose tissue and increasing the risk of developing asthma) has also been shown to connect childhood BMI with childhood-onset asthma." (PMID 37686844, 2023). "Thus, we performed a meta-analysis to accurately investigate the association between IL-6 and asthma." (PMID 37173781, 2023). "Furthermore, EPs 7630 prevented asthma attacks in children triggered by rhinovirus by decreasing the inflammation caused by increases in IL-6, IL-8, and IL-16." (PMID 37765014, 2023). "The IL-6-induced inflammatory pathway increased the inflammatory response causing microvascular dilation and muscle contraction, two processes responsible for edema and airway narrowing during asthma attacks in humans." (PMID 36743692, 2023). "Previous studies have linked IL-6 signaling to severe asthma." (PMID 38062491, 2023). "Higher serum IL-6 levels also show association with metabolic syndrome and severe asthma." (PMID 38062491, 2023). "Our in vivo and in vitro experiments showed that SZYQD and its main active component luteolin play a therapeutic role in relieving asthma symptoms by reducing inflammation and mucus overproduction, which was associated with decreased IL-6 and MUC5AC expression." (PMID 38093206, 2023). "Our results also show a trend toward lower sputum neutrophil numbers and blood eosinophil counts in patients characterized by high IL-6 + sIL-6Rα gene expression suggesting an association between IL-6 + sIL-6Rα signaling and paucigranulocytic or type-2 low asthma that warrants further investigation." (PMID 38062491, 2023). "In white matter, asthma moderated the influence of IL-6 on dMRI metrics such that in asthma, higher IL-6 concentrations were associated with higher values of NDI and FA, as well as lower MD, RD, AD, ODI, whereas this relationship was absent in the control group." (PMID 37377978, 2023).
asthma (continued). "Both IL-1 and IL-6 are implicated in the pathogenesis of asthma." (PMID 37377967, 2023). "Furthermore, we evaluated the association of an IL-6 signaling signature to different asthma-related phenotypes in bronchial biopsies and nasal brushes of asthma patients and controls." (PMID 38062491, 2023). "A recent prospective study identified a causal relationship between circulating IL-6 and asthma exacerbations, which could be plausibly explained by IL-6-driven differentiation of naïve T cells into Th17 cells that trigger asthma exacerbation." (PMID 36032162, 2022). "Limited data are available on the types of asthma-associated immune responses under IL-6 blockade." (PMID 35408882, 2022). "In the context of allergic airway inflammation, both TNF and IL-6 overproduction may trigger different inflammatory pathways implicated in asthma pathogenesis." (PMID 35408882, 2022). "Additionally, Th17 pathways, ILC3 that expresses both IL-17 and IL-22, and IL-6 have been associated with obesity-related asthma." (PMID 36078171, 2022). "In addition, epithelial IL6 trans-signaling has been identified as a potential mechanism linked to asthma phenotypes characterized by increased airway inflammation." (PMID 36140412, 2022). "We included allergic rhinitis, atopic dermatitis, and asthma in this study, hoping to explore whether IL-6 polymorphisms were the common risk variants of allergic diseases." (PMID 35368692, 2022). "Tryptase increases the expression of CCL2 and the pro-inflammatory cytokines IL-6 and IL-22 by epithelial cells; induces airway smooth muscle contraction and fibrinogen degradation, all of which contribute to airway obstruction associated with asthma." (PMID 35266441, 2022). "IL-6 and C-reactive protein have been linked to severe asthma." (PMID 36078171, 2022). "Altogether, our study suggested that the underlying mechanisms for the association between childhood BMI and childhood-onset asthma might involve IL-6 and adiponectin." (PMID 36253437, 2022). "IL-6 trans-signaling has a pathogenic role in asthma severity-related airways." (PMID 35052792, 2022). "IL-6 has been reported to be associated with loss of central airway function in asthma and a recent analysis from the SARP consortia reported that a sub-population of severe asthmatics with elevated serum IL-6 experienced poorer lung function and higher exacerbation rates." (PMID 34022896, 2021). "In addition, the asthma risk allele at rs4792901 was associated with increased serum IL6 levels (P = 0.041) in 651 healthy adults." (PMID 34552174, 2021). "One line of inquiry could examine the possibility that TLR10 dampens TLR2 signaling and IL6 production, thereby increasing the risk of asthma." (PMID 34103634, 2021). "The hypothesized mechanism causing this phenotype of asthma is a macrophage-dependent inflammation of the adipose tissue resulting in a pronounced release of IL-6, TNF-α, and leptin that can be reversed with a weight loss." (PMID 35055325, 2021). "However, a significant association was observed between baseline IL-6 level and the probability of experiencing an asthma exacerbation treated with systemic corticosteroids during the 1-year study." (PMID 33418879, 2021). "Previous studies have shown that IL-6 and IL-17A are associated with airway remodeling in asthma." (PMID 34526979, 2021). "Genome-wide association studies (GWAS) have also reported that the single nucleotide polymorphism (SNP) rs2228145 (Asp358Ala)—a variant in IL6R that increases IL-6R shedding and promotes IL-6 trans-signaling—is associated with asthma prevalence, asthma severity, and lower pulmonary function." (PMID 33912579, 2021). "The important pro-inflammatory factor IL-6 induces the polarization of initial T cells to T helper cell 17 (Th17) cells and is in turn associated with neutrophil recruitment that can aggravate airway inflammation in asthma." (PMID 34402724, 2021).